TIA1 (TIA1 cytotoxic granule associated RNA binding protein)
Diseases named in the same sentence as TIA1 in open-access papers (continued):
Sharing a sentence is not in itself a finding about the gene and the disease.
bladder tumors (1 paper, 2025). "In curated bladder tumor cohorts, higher TIA1 levels showed an association with favorable survival." (PMID 41300366, 2025). "Pan-cancer analysis of TCGA revealed that TIA1 is broadly expressed, with significantly higher transcript levels in bladder tumors than in matched normal urothelium." (PMID 41300366, 2025). "To determine whether the TIA1-dependent, anti-glycolytic effect we observed in vitro also operates in a physiologically intact, immune-competent setting, we turned to an orthotopic MB49-Luc bladder tumor model in C57BL/6J mice." (PMID 41300366, 2025).
brain tumour (1 paper, 2023). "Alterations in RBP expression levels and function have been associated with neurological disorders (e.g. HNRNPA1, MATR3, TIA1, and TARDBP and brain tumour development (e.g. Musashi1, SERBP1, PTB and HuR." (PMID 37294214, 2023).
carcinoma in situ (1 paper, 2016). "In carcinoma in situ and advanced cancers, TIA1 staining was observed in both the cytoplasm and the nucleus, and cytoplasmic TIA1 immunoreactivity was higher in advanced cancers than in carcinoma in situ." (PMID 26958940, 2016).
cervical carcinoma (1 paper, 2015). A carcinoma arising from either the exocervical squamous epithelium or the endocervical glandular epithelium. "Interestingly, TIA-1 shares an 80% amino acid homology with TIAR and is downregulated by TIAR at the translational level in human cervical carcinoma (HeLa) cells." (PMID 25918534, 2015).
dengue (1 paper, 2017). "Our group also reported other activation markers such as CD69 and TIA1 as upregulated in mild dengue patients." (PMID 29038620, 2017).
depression (1 paper, 2021). "This novel finding may provide a new therapeutic target by inhibiting the miR-34a-5p/Tia1 pathway to prevent radiation-induced pathogenesis of depression." (PMID 34572124, 2021).
esophageal carcinoma (1 paper, 2022). A primary or metastatic malignant neoplasm involving the esophagus. "An oncogenic or tumor suppressive function of TIA1 could be highly dependent on its subcellular localization as previously suggested in esophageal carcinoma, where TIA1-dependent deregulations of both ONC and TS were found, similarly to our observations." (PMID 35406476, 2022).
Hodgkins lymphoma (1 paper, 2013). A heterogeneous group of malignant lymphoid neoplasms of B-cell origin characterized histologically by the presence of Hodgkin and Reed-Sternberg (HRS) cells in the vast majority of cases. "Further, 13.7% of stage-IIIB/IV Hodgkin's lymphoma showed expression of TIA-1 in tumor cells, despite its supposed T/NK specificity." (PMID 23738160, 2013).
IgG4-related disease (1 paper, 2025). "Given that TFR cells have been implicated in suppressing GZMK+ cytotoxic TFH cells in ectopic lymphoid follicles of patients with IgG4-related disease, we assessed the ratio of GZMK+TIA-1+ or GZMB+TIA-1+ TFK cells to TFR cells." (PMID 41030456, 2025).
liver diseases (1 paper, 2022). "Collectively, our data on TIA1 reinforce the idea that alterations in post-transcriptional regulators of gene expression, such as AUBPs, are relevant in liver diseases and HCC." (PMID 35406476, 2022). "The pleiotropic role for TIA1 in metabolism and cancer likely also depends on its functional interactions with various other cellular factors differentially expressed in different stages of these hepatic diseases, such as non-coding RNAs or other AUBPs." (PMID 35406476, 2022).
liver tumors (1 paper, 2012). "As we have detected an inverse correlation of TIA1 and IGFBP3, it could be assumed that this suppressive mechanism could act in pediatric liver tumors." (PMID 22401581, 2012).
lymphopenia (1 paper, 2022). Reduction in the number of lymphocytes. "Altogether, our results reveal that TIA1 and TIAL1 play essential, but redundant, roles during the development of B cells, and that peripheral lymphopenia is due to a severe block at the pro-B cell stage." (PMID 36543128, 2022).
melanocytic neoplasm (1 paper, 2021). "TIA‐1 expression was observed in 3.7% of the infiltrating immune cells in the spitzoid melanocytic neoplasms." (PMID 32970867, 2021).
Neurofibrillary tangles (1 paper, 2021). Pathological protein aggregates formed by hyperphosphorylation of a microtubule-associated protein known as tau, causing it to aggregate in an insoluble form. "TIA1 is involved in RNA splicing and post-transcriptional gene regulation, has been found in stress granules, and has been related to tau oligomerization and neurofibrillary tangle deposition in AD." (PMID 34572457, 2021).
NK-cell enteropathy (1 paper, 2022). "The EGD examination of the third patient revealed small superficial ulcers over the infrapapillary region of the duodenum, and the biopsy revealed mucosal infiltrates of mononuclear cells with a positive NK cell phenotype (CD3+/CD45+/CD56+/TIA-1+), which was consistent with NK cell enteropathy." (PMID 35935715, 2022).
Opportunistic infection (1 paper, 2012). An infection that is caused by a pathogen that would generally not be able to cause an infection in a host with a normal immune system. "These opposite alterations may occur because cytotoxic T cells are prevalent in the portal tract in ACR cases, while monocytes and neutrophils, which also release TIA-1, are more popular in lobular in biliary complications, opportunistic infections, and preservation/reperfusion injuries." (PMID 23111143, 2012). "By contrast, during other complications such as biliary complications, opportunistic infections, and preservation/reperfusion injuries, TIA-1-positive cells significantly increased in lobules but not in the portal tract area." (PMID 23111143, 2012). "In the lobules, perforin- and granzyme B-positive cells in the ACR group were significantly more than those in the biliary complication and opportunistic infection groups, while TIA-1-positive cells was significantly fewer than those in non-ACR groups." (PMID 23111143, 2012).
Parkinsonism (1 paper, 2017). Characteristic neurologic anomaly resulting from degeneration of dopamine-generating cells in the substantia nigra, a region of the midbrain, characterized clinically by shaking, rigidity, slowness of movement and difficulty with walking and gait. "Interestingly, none of our TIA1 mutation carriers developed significant parkinsonism or psychotic features, both of which are commonly reported in series with the C9orf72 mutation." (PMID 29216908, 2017).
peripheral T-cell lymphoma (1 paper, 2006). "The tumour cells were CD4+, CD5+ but lacked EMA, TIA-1, CD56 and EBV expression and the diagnosis was a CD30+ peripheral T-cell lymphoma unspecified." (PMID 16623775, 2006).
primary progressive aphasia (1 paper, 2017). Primary progressive aphasia (PPA) is a neurodegenerative disorder, characterized by a primary dissolution of language, with relative sparing of other mental faculties for at least the first 2 years of illness. "The high frequency of primary progressive aphasia (PPA) in our TIA1 mutation carriers is different from those with the C9orf72 mutation whose FTD phenotype is more often bvFTD." (PMID 29216908, 2017).
proteinopathy (1 paper, 2023). "Illustratively, a SQSTM1 variant known to cause a multisystem proteinopathy through stress granule impairment was enhanced synergistically by a variant in TIA1, gene annotated to cause a distinct myopathy." (PMID 38239855, 2023).
psoriasis (1 paper, 2014). An autoimmune condition characterized by red, well-delineated plaques with silvery scales that are usually on the extensor surfaces and scalp. "CXCR3, CXCL10, and TIA-1 were elevated in periadnexal sites of DLE lesional skin versus psoriasis lesional skin." (PMID 24744689, 2014). "Thus, we compared expression of T cell, B cell, and macrophage markers and their associated proteins, TIA-1, CXCR3, and CXCL10 in DLE lesional skin, psoriasis lesional skin, and normal skin." (PMID 24744689, 2014). "These periadnexal areas also contained higher expression of TIA-1, CXCR3, and CXCL10 in DLE versus psoriasis lesional skin." (PMID 24744689, 2014).
rectal cancer (1 paper, 2014). A primary or metastatic malignant neoplasm that affects the rectum. "Of all tested markers, only CD8 (P = 0.005) and TIA-1 (P = 0.05) were significantly more frequently detectable in early rectal cancer biopsies of node negative as compared to node positive patients." (PMID 25609852, 2014).
retinal degeneration (1 paper, 2023). Degeneration of the retina. "Interestingly, Tia1-positive SG accumulations were abundant especially at early stages of retinal degeneration (P17), and they appeared less frequently at a later stage (P26) (right panel P26)." (PMID 37048167, 2023).
rhabdomyosarcoma (1 paper, 2018). A rare aggressive malignant mesenchymal neoplasm arising from skeletal muscle. "Similar results were observed in EV71-infected rhabdomyosarcoma (RD) cells, suggesting that the persistent SGs containing TIA-1, TIAR, and Sam68 might not be tSGs." (PMID 29415027, 2018).
rheumatic diseases (1 paper, 2015). "We identified a total of eight differentially expressed genes (TNFSF10, CX3CR1, LY96, TLR5, TXN, TIA1, PRKCH, PRF1), each associated with at least 3 of the 4 studied rheumatic diseases." (PMID 26352601, 2015). "By jointly analyzing 6 published microarray gene expression datasets about RA, SLE, OA and AS, we identified eight genes (TNFSF10, CX3CR1, LY96, TLR5, TXN, TIA1, PRKCH, PRF1) presenting general importance to rheumatic diseases." (PMID 26352601, 2015).
soft tissue sarcoma (1 paper, 2008). A malignant neoplasm arising from muscle tissue, adipose tissue, blood vessels, fibrous tissue, or other supportive tissues excluding the bones. "TIA-1, which encodes an RNA-binding protein with translation-regulatory functions has already been reported to be up-regulated in tumor specimens post-treatment with TNF alpha in soft tissue sarcomas." (PMID 18959781, 2008). "It was further hypothesized that TIA-1 could mediate death receptor mediated apoptosis in soft tissue sarcoma and that its overexpression might sensitize endothelial cells to proapoptotic stimuli present in the tumor microenvironment and enhance NK cell cytotoxic activity against cancer cells." (PMID 18959781, 2008).
T-cell neoplasms (1 paper, 2020). "From the immunohistochemical results, decreased MAX expression correlated with the expression of cytotoxic molecules such as TIA-1 and granzyme B. Recent reports have shown that expression of cytotoxic molecules may be independent prognostic factors in mature T-cell neoplasms including ALCL21–23." (PMID 32587329, 2020).
ZIKV infection (1 paper, 2019). "We also investigated the role of different stress granule proteins in ZIKV infection by using target-specific short interfering RNAs to deplete Ataxin2, G3BP1, HuR, TIA-1, TIAR, and YB1." (PMID 30944179, 2019). "Because TIA-1 and TIAR were previously shown to promote WNV replication, we also investigated the role of TIA-1 and TIAR during ZIKV infection." (PMID 30944179, 2019).
tumor (106 papers, 2006 to 2026). "Our findings recast TIA1—from a classical stress granule component to a gatekeeper of immunometabolism that aligns with BCG-associated tumor control in our models." (PMID 41300366, 2025). "The expression of NKG7/TIA-1 is critically linked to anti-tumor responses, particularly in CD8+ T cells." (PMID 41030456, 2025). "In contrast, in immortalized or tumor cells, transient or stable downregulation of TIA1, TIAR or both enhances cell proliferation and is associated with a tumorigenic phenotype." (PMID 35163320, 2022). "Regarding TIA-1+ infiltrates we found that patients with the tumor located in the PT were more susceptible to TIA-1+ cells and the infiltration of these cells conferred superior survival to patients that were treated with neoadjuvant chemotherapy." (PMID 34885185, 2021). "Perforin was expressed by the tumor cells, while other cytotoxicity-associated markers (granzyme B and TIA1 [Tia1 cytotoxic granule-associated rna binding protein]) remained negative (data not shown)." (PMID 32845352, 2020). "Because of the myriad of tumor suppressor functions of TIA1, it is imperative that we elucidate the mechanisms underlying how TIA1 is regulated during tumorigenesis, especially in CRC." (PMID 28257633, 2017). "We also assessed the association between B7-H1 and B7-H3 expression on tumor cells and TIA-1 and IFN-γ expression on TILs." (PMID 25609202, 2015). "This, together with the effect of cytotoxic molecules, including perforin, granzyme B and TIA-1 released by the malignant NK cells, and together with the tumour-associated inflammatory process, cause the widespread tissue damage and necrosis." (PMID 23327615, 2013). "Trastuzumab treatment was associated with significantly increased numbers of tumour-associated NK cells and increased lymphocyte expression of Granzyme B and TiA1 compared with controls." (PMID 16404427, 2006). "In our models, increased TIA1 expression was associated with slower tumor growth." (PMID 41300366, 2025). "Whether the potential tumor suppressor function of TIA-1 is associated with its cell death functions remains to be determined." (PMID 36231015, 2022). "However, a short splicing variant of TIA-1 expressed in human colon cancer has been shown to exert the opposite effects by enhancing tumor growth, angiogenesis, and chemoresistance, adding complexity to the participation of SG proteins in cancer." (PMID 34095105, 2021). "However, these analyses also revealed that the enhanced tumor initiation triggered by TIA1 downregulation was associated with an increased expression of ONCs previously identified in HepG2 cells (e.g., Spp1, Ccn2), following TIA1 silencing." (PMID 35406476, 2022). "On the one hand, TIA1 functions as a tumor suppressor during early stages of tumorigenesis, with downregulated in human HCC tissues." (PMID 41425091, 2025). "Conversely, enforced expression of wild-type TIA1 alone curtailed orthotopic tumor growth, establishing sufficiency." (PMID 41300366, 2025). "Another study on miR-19a underscored its role in promoting CRC cell proliferation and migration and facilitating tumor growth in vivo by targeting TIA1." (PMID 40871106, 2025). "In vitro, TIA1 knockdown enhances tumor cell migration and proliferation, whereas in vivo mouse models suggest a tumor-suppressive function." (PMID 41425091, 2025). "High expression of TLR2–TRR6 heterodimer in colonic epithelial cells, when activated by DAMP, can increase the expression of tumor suppressor factors such as glycoproteins and T‐cell antigen‐1 (TIA1), thereby preventing tumor progression and invasion." (PMID 40727252, 2025). "Conversely, TIA1 over-expression alone limited tumor growth and recapitulated BCG-mediated glycolytic restraint and T-cell activation." (PMID 41300366, 2025). "TIA1 also showed an inverse correlation with tumor purity, consistent with greater overall immune infiltration in TIA1-high tumors." (PMID 41300366, 2025).
tumor (continued). "Immunohistochemistry in 40 paired specimens showed a marked reduction in the TIA1 protein in tumor epithelium compared with adjacent normal tissue (median H-score 38 vs. 125; **** p < 0.0001), underscoring its clinical relevance." (PMID 41300366, 2025). "The tumor cells also express cytotoxic molecules, including TIA-1 and granzyme B, whereas CD3 and CD7 are always diminished or lost." (PMID 38792976, 2024). "Consistently, TIA-1 is down-regulated in a variety of human tumors, and its knockdown promotes tumor growth and invasion in mice." (PMID 36231015, 2022). "This has led to the conclusion that in these latter cancers, TIA1 regulates the expression of genes that favor pro-tumor progression, pointing to TIA1 as a potential oncogene and prognostic marker." (PMID 35163320, 2022). "Based on these major differences between our in vitro and in vivo models, we suggest a dual and complex role for TIA1 depending on the cellular context, metabolic status and tumor microenvironment." (PMID 35406476, 2022). "In this study, all patients with positive HLA-DR also presented infiltration of CD8-positive and TIA-1-positive T cells and expression of HLA-class I molecules in tumor cells, and they responded to ICI therapy." (PMID 35739295, 2022). "In this context, TIA1 exerts a dual function, as it has been shown that depending on the processes regulated in different cancers, it can act both as a tumor suppressor and an oncogene." (PMID 35163320, 2022). "Our study provides new insights regarding the role for TIA1 in HCC and questions the current concept of TIA1 as a strict tumor promoter." (PMID 35406476, 2022). "In contrast, our in vitro data indicated that TIA1 expression promoted proliferation and migration in HCC cell lines, thus suggesting a dual and context-dependent role for TIA1 in tumor initiation versus progression." (PMID 35406476, 2022). "When stained, PD-L1, Foxp3, CD8, TIA-1 were expressed diversely in tumor cells and tumor-infiltrating lymphocytes." (PMID 34275008, 2022). "T cell responses were analyzed through immunohistochemistry (IHC) staining for CD3, CD4, CD7, CD8, CD25, TIA‐1, HLA‐DR, and Ki67 (proliferative marker) on tumor biopsy samples." (PMID 35790025, 2022). "B7-H4 was mainly expressed on the surface in tumor cells, while CD8 and TIA-1 were often expressed in tumor-infiltrating lymphocytes." (PMID 34275008, 2022). "Contrastingly, overexpression of TIA1 in tumor lines leads to a cell-quiescence phenotype that ultimately triggers cell death by apoptosis and autophagy." (PMID 35163320, 2022). "Previous studies had reported that miR-206 repressed ATC metastasis by targeting MRTF-A, and miR-599 functioned as a tumor suppressor in ATC through targeting T-cell intracellular antigen (TIA1)." (PMID 32336952, 2020). "TIA1 can also be used to supplement prognostic information related to TNM (tumor, node, and metastases) stage and adjuvant therapy in mismatch repair-proficient colorectal cancer patients." (PMID 31440515, 2019). "Cytotoxic markers for ENKL diagnosis include TIA-1, granzyme B, T-cell intracellular antigen 1 and perforin on tumor cells." (PMID 31139570, 2019). "TIA1 is thought to be a new member of the tumor suppressor family, as TIA1 regulates, modulates and/or interacts with many types of mRNA involved in cancer cell proliferation, apoptosis, angiogenesis, invasiveness and metastasis as well as in immune evasion." (PMID 28257633, 2017). "For example, it has been reported that knockdown of TIA1 triggers cell proliferation and invasion as well as tumor growth." (PMID 28257633, 2017). "In conclusion, CD8/Tia1 citotoxic T-lymphocytes emerge as an important player in anti-tumor immune response." (PMID 29340095, 2017). "The overexpression of TIA1 attenuated the growth-promoting effects of miR-19a, suggesting that miR-19a promotes tumor growth by silencing TIA1." (PMID 28257633, 2017).